TRPV1 (transient receptor potential cation channel subfamily V member 1)
Diseases named in the same sentence as TRPV1 in open-access papers (continued):
Sharing a sentence is not in itself a finding about the gene and the disease.
ischemia (continued). "Moreover, FAAH inhibition was found to have neuroprotective effects in rat models of high intraocular pressure (IOP)-induced ischemia and optic nerve axotomy by enhancing eCB levels that acted on both CB1Rs and TRPV1 channels." (PMID 36231760, 2022). "Administration of a TRPV1 antagonist elevates myocardial damage in isolated wild-type hearts, suggesting that TRPV1 may have a protective effect in ischemia-reperfusion injury, with links to the release of SP." (PMID 33193423, 2020). "Although the mechanisms responsible for the varying effects of TRPV-1 agonists on cardiomyocytes remain unclear, a recent report suggested that OLDA attenuates ischemia/reperfusion injury of hearts via TRPV-1 activation." (PMID 26888607, 2016). "Consequently, our study unravels that TRPV1 inhibition by LA during ischemia prevents the multimodal nerve terminal from further depolarization." (PMID 27827430, 2016). "The beneficial effects of capsaicin may involve release of a substance from TRPV1-expressing nerve endings that exerts a protective action against ischemia/reperfusion-induced kidney injury." (PMID 25330307, 2014). "In this study, we found that Evo, extracted from E. rutaecarpa, has the ability to induce survival autophagy in astrocytes through TRPV1-dependent signaling, which may provide a possible option for ischemia treatment." (PMID 24454492, 2013). "We tested whether stimulation of TRPV1-expressing nociceptive afferent fibers with capsaicin also affect ischemia-induced inward currents." (PMID 17459156, 2007). "Our hypothesis was that treatment with CS would activate TRPV1 in the heart under conditions of ischemia and reperfusion, restoring control of Ca2+ flow into cells and elevating the bioavailability of NO, thereby reducing ROS and enhancing the cardioprotective mechanisms." (PMID 35164296, 2022). "Despite the still incomplete evidence regarding the circumstances and timing when TRPV1 may signal either pro-inflammatory or anti-inflammatory effects, TRPV1 activation appears to play a role in the severity of effects on cerebral tissue induced by hypoxic ischemia and ischemia/reperfusion." (PMID 35408995, 2022). "TRPV1 is located on the cardiac sensory nerves and might function as a molecular sensor to detect tissue ischemia and activate cardiac nociceptors because a selective antagonist of TRPV1, iodoresiniferatoxin attenuates both bradykinin- and ischemia-induced firing of cardiac spinal afferent nerves." (PMID 32039693, 2020). "The fact that TRPV1 is expressed during ischemia allows us to speculate that TRPV1 inhibits the opening of the mitochondrial transition pore and regulates Ca2+ flux, which leads to its possible participation in the control of the cell damage pathways that are activated during ischemia." (PMID 35164296, 2022). "The findings further suggest that NGF is likely responsible for enhanced TRPV1, P2X3, and ASIC3 and plays a role in modulating the metaboreceptor component of the EPR in the hindlimb muscle ischemia." (PMID 22934005, 2012). "Intraspinally injected FeNCs-TRPV1 induced TRPV1 desensitization in rats exposed to repetitive and transient ACMF before ischemia, resulting in the inhibition of TRPV1-mediated Ca2+ signaling and neuropeptide release in the spinal cord during myocardial ischemia and reperfusion." (PMID 41387112, 2025). "Since the expression of TRPV1 and the levels of CGRP in cardiac tissue increased during ischemia and during reperfusion while PDE-3 and MDA decreased, we propose that CGRP may be one of the mediators of cardioprotection." (PMID 35164296, 2022). "Another research showed that compared with non-diabetic rats, the decrease of TRPV1 expression level in myocardium of diabetic rats after myocardial ischemia could lead to the loss of cardioprotection function and impair myocardial function after ischemia treatment." (PMID 36452230, 2022).
ischemia (continued). "Therefore, the activation of TRPV1 may protect the heart by regulating oxidative stress, the NO pathway, and by controlling the flow of Ca2+ to prevent damage to the cardiac tissue when the proper functioning of the heart is compromised, as in ischemia and reperfusion." (PMID 35164296, 2022). "In brief, our results showed that OXC-induced hypothermia after transient forebrain ischemia effectively protected against ischemia–reperfusion injury through an increase in TRPV1 expression in the gerbil hippocampal CA1 region, indicating that TRPV1 is involved in OXC-induced hypothermia." (PMID 35008663, 2021). "We previously demonstrated that pharmacological activation of TRPV1 using CAP conferred a cardioprotective effect against ischemia/reperfusion injury and that pharmacological inhibition or genetic deletion of TRPV1 enhanced ischemia/reperfusion injury." (PMID 25314299, 2014). "The acid sensitive ion channels TRPV1 (transient receptor potential vanilloid receptor-1) and ASIC3 (acid sensing ion channel-3) respond to tissue acidification in the range that occurs during painful conditions such as inflammation and ischemia." (PMID 16813657, 2006). "This suggests, TRPV1 antagonist, and absence of TRPV1 channels, may decrease detrimental inflammatory responses during ischemia-reperfusion injury, thus providing neuroprotection." (PMID 39965247, 2025). "However, on an ischemia-induced neuronal injury, AM404 protected CA1 layer neurons of the hippocampus through CB1 and opioid receptors but not involving TRPV1, and prevented ischemia-induced memory impairment." (PMID 31920563, 2019). "In addition to TRPV1, P2X3, and ASIC3, it needs to point out that other muscle afferents’ receptors including μ-opioid and thromboxane (TP) receptors are engaged in processing chronic ischemia of the hindlimb muscles." (PMID 22934005, 2012). "The present findings suggest that ROS produced by transient hindlimb ischemia/reperfusion evokes spontaneous licking through activation of TRPA1, but not TRPV1." (PMID 26983498, 2016).
epilepsy (42 papers, 2015 to 2026). A brain disorder characterized by episodes of abnormally increased neuronal discharge resulting in transient episodes of sensory or motor neurological dysfunction, or psychic dysfunction. "We summarize the most advanced drug candidates derived from BmK defensins and short-chain toxins, which exhibit activity against Kv1.3, BK, TRPV1, and other channels implicated in epilepsy, neuroinflammation, glioma, and pain." (PMID 41693793, 2026). "Conversely, TRPV1 channel activity has been implicated in epilepsy having a role in neuronal excitability and synaptic transmission (Nazıroglu, 2015)." (PMID 32608035, 2020). "These indicate that astrocytic TRPV1 is not only a switch of pro-inflammatory factor but also a susceptibility gene for the induction of epilepsy following HIBD." (PMID 31722723, 2019). "Extensive evidence suggests that TRPV1 can be linked to epilepsy, although causal determination remains unclear." (PMID 38404644, 2024). "Of the 30 protein coding genes with identified coding sequence or expression differences, ten had a prior association with seizure or epilepsy based on literature and database searches, including Aspa, Hic1, Nlrp1a, Nlrp1b, Pafah1b1, Smg6, Trpv1, Trpv3, Ywhae and 6330403K07Rik." (PMID 35606653, 2022). "Therefore, we continued to validate the underlying mechanisms of TRPV1 as a potential target for epilepsy." (PMID 31722723, 2019). "Moreover, we demonstrated TRPV1 played a pro-epileptogenesis role in HI mice model (24 h) due to the result that epilepsy susceptibility was significantly decreased in TRPV1 deficiency mice compared with WT mice after HIBD." (PMID 31722723, 2019). "Therefore, this study was aimed to investigate the role of TRPV1 on astrocytes in the epilepsy susceptibility after neonatal HIBD." (PMID 31722723, 2019). "Additionally, inhibition of TRPV1 by capsazepine suppressed seizure susceptibility in the genetically epilepsy-prone rat." (PMID 31263706, 2019). "TRPV1, a calcium-permeable channel, is a cause of epilepsy and expressed in the hippocampus." (PMID 28423368, 2017). "Therefore, it remains to be further studied the underlying mechanism of hippocampal TRPV1 function in epilepsy." (PMID 25713512, 2015). "However, neurobehavioral studies have recently demonstrated that TRPV1 is broadly expressed in the brain and critically implicated in neurological and mental disorders, such as epilepsy/seizure, anxiety, and neurodegenerative diseases." (PMID 31680864, 2019). "A recent study showed that hypoxia‐ischemia induced TRPV1 upregulation in astrocytes promotes the occurrence of epilepsy by increasing the proinflammatory cytokines release, such as TNF‐α, IL‐6, IL‐1β, and iNOS." (PMID 41399206, 2025). "Increased expression of TRPV1 was also observed after the successful induction of temporal lope epilepsy through kindling (audiogenic epilepsy) in rats." (PMID 38404644, 2024). "Increased TRPV1 expression in epilepsy suggests its involvement in regulating cortical excitability." (PMID 38891938, 2024). "This interaction, linked to the desensitization and internalization of TRPV1, positions CBD as a potential pharmacotherapeutic treatment in conditions where TRPV1′s inhibition is crucial, such as pain, epilepsy, and, potentially, glaucoma." (PMID 38256192, 2024). "On the other hand, pre-treatment with the TRPV1 antagonist capsazepine decreased seizure severity and mortality in pentylenetetrazol-induced epilepsy (GABAA antagonist)." (PMID 38404644, 2024). "This again suggested that TRPV1 channels play a pivotal role in the epileptogenesis process, indicating their well-known role in epilepsy-related brain damage mechanisms, such as excitotoxicity, glutamate release, and neuronal apoptosis." (PMID 37744878, 2023). "Using capsazepine, 5′-iodoresiniferatoxin, and resolvins, the authors showed that inhibition of the TRPV1 channel induced protective effects against epilepsy and epilepsy-induced Ca2+ entry in the hippocampal and DRG neurons." (PMID 33748103, 2021).
epilepsy (continued). "A massive amount of evidence has demonstrated that hyperactivation/overexpression of TRPV1 contributes to epilepsy and neuroinflammation-induced seizures." (PMID 34062987, 2021). "For instance, TRPV1 is currently considered to be an anticipated molecular target for the clinical evaluation of epilepsy therapy." (PMID 32377171, 2020). "For this reason, we provide a brief description of the TRPV1 effects in preclinical and clinical models of epilepsy." (PMID 33202963, 2020). "Systemic administration of TRPV1 antagonists seems to be a novel therapeutic target for epilepsy, given their antiepileptic, antiepileptogenic or neuroprotective effects in preclinical models." (PMID 33202963, 2020). "In the present study, we demonstrated that TRPV1 deficiency reversed OGD-induced increase in neuronal excitability comparing with control astrocytes and HIBD-induced increased epilepsy susceptibility comparing with WT mice." (PMID 31722723, 2019). "However, the role of TRPV1 in epilepsy susceptibility after neonatal HIBD is unknown." (PMID 31722723, 2019). "Activation of microglial TRPV1 promotes the release of excitotoxicity pro-inflammatory molecules and maintains persistent neuroinflammation, which is a critical etiology of epilepsy/seizures." (PMID 31680864, 2019). "To further investigate the role of hippocampal TRPV1 in the epilepsy, we administrated TRPV1 agonist CAP and antagonist CPZ directly into the hippocampus area." (PMID 25713512, 2015). "The expression of TRPV1 protein was significantly increased in the hippocampus and cortex of subjects with epilepsy." (PMID 25713512, 2015). "The effects of TRPV1 agonist on epilepsy will be studied further in consideration of TRPV1 desensitization and its different effects on various brain areas in future research." (PMID 25713512, 2015). "Then, to clarify the function of hippocampal TRPV1 on epilepsy, the agonist and antagonist of TRPV1 were administrated into hippocampus respectively to detect the effects on PTZ-induced seizures." (PMID 25713512, 2015). "Overall, this review demonstrated that PEA, a naturally occurring N-acylethanolamine whose biological effects are related to indirect activation of CB1 receptors as well as PPAR-α and TRPV1 modulation, may be involved in seizures and epilepsy." (PMID 35053844, 2022). "Similarly, despite TRPV1 channels being closely related with epilepsies and their comorbidities, possible neuroplastic alterations in their expression have never been analyzed, either in WARs or in other genetic models of audiogenic seizures." (PMID 35203625, 2022). "Furthermore, changes in TRPV1 expression and/or activity are recognized as major contributors to the etiology of epilepsy in humans." (PMID 34062987, 2021). "To determine whether Trpv1 expression may contribute to the epilepsy phenotype of Scn1a+/− mice, we compared the cortical mRNA levels from WT and Scn1a+/− mice on both 129S6/SvEvTac and on [129S6/SvEvTac × C57BL/6J]F1 (129 × B6) genetic backgrounds." (PMID 34079465, 2021). "In fact, a recent study suggested that the activation of the TRPV1 channel may play a key role in the development of epilepsy." (PMID 33748103, 2021). "Increasing evidence suggests that TRPV1 is involved in the regulation of synaptic plasticity, the synaptic remodeling of learning, memory process, and also many neurological diseases such as epilepsy, Alzheimer's disease, and Parkinson's disease." (PMID 32337274, 2020). "Further support for this hypothesis comes from other studies showing that TrpV1 expression in hippocampus is increased in animal models of epilepsy." (PMID 31701438, 2020). "Because TRPV1 regulates neuronal excitability, this channel could be a promising therapeutic target for the treatment of epilepsy." (PMID 33202963, 2020). "Studies also concluded that TRPV1 can be a potential target in the treatment of epilepsy." (PMID 32337274, 2020). "Taken together, these findings support the role of TRPV1 in the etiology of epilepsy." (PMID 33202963, 2020).
epilepsy (continued). "Taken together, TRPV1 was involved in the CNS inflammatory response and epilepsy, which may lead to neurotoxicity." (PMID 31722723, 2019). "Besides, transient receptor potential banilloid type 1 (TRPV1) and gap junction blockers, which have been reviewed in recent studies, are potential drug targets in epilepsy therapy." (PMID 28423368, 2017). "Taken together, our findings support that systemic administration of TRPV1 antagonist may be a novel therapeutic target for epilepsy, and hippocampal TRPV1 plays an important role in epileptogenesis." (PMID 25713512, 2015). "In summary, our results indicate that systemic administration of TRPV1 antagonist may be a new potential therapeutic target for epilepsy treatment, and hippocampal TRPV1 exerts important role in epilepsy." (PMID 25713512, 2015). "Our findings suggest that the systemic administration of TRPV1 antagonist may be a novel therapeutic target for epilepsy, and alteration of hippocampal TRPV1 function exerts a critical role in seizure susceptibility." (PMID 25713512, 2015). "Transient receptor potential vanilloid 1 (TRPV1) is widely distributed in the central nervous system (CNS) including hippocampus, and regulates the balance of excitation and inhibition in CNS, which imply its important role in epilepsy." (PMID 25713512, 2015). "In the present study, we demonstrated that increased TRPV1 immunoreactivity in limbic brain structures, such as the hippocampus and BLA, is associated with genetic susceptibility to epileptic seizures and increased anxiety-like behavior in a genetic model of epilepsy, the WAR strain." (PMID 35203625, 2022). "Thus, the increased TRPV1 expression endogenously detected in the hippocampus and BLA of WARs is in line with previous neuroplastic alterations and add new information regarding epilepsy susceptibility and calcium mobilization in these limbic brain sites." (PMID 35203625, 2022). "However, it is unknown whether Trpv1 is an anticonvulsant drug target in animal models of drug-resistant epilepsies." (PMID 34079465, 2021). "Thus, we examined whether Trpv1 affects the epilepsy phenotype of the F1.Scn1a+/− mouse model of DS." (PMID 34079465, 2021). "Additionally, in recent years, extensive research has been directed towards studying TRPV1, because it is also involved in the pathophysiology of diseases such as schizophrenia, stroke, pain, depression, anxiety, Parkinson’s disease and epilepsy." (PMID 33202963, 2020). "Thus, it is not surprising that TRPV1 is currently implicated not only in pain transduction, but also in several neurological and psychiatric disorders such as epilepsy, anxiety, and depression as well as drug-addiction disorders." (PMID 31263706, 2019). "Therefore, we focus on the role of astrocytic TRPV1 in neuroinflammation in HIBD-induced epilepsy." (PMID 31722723, 2019). "Furthermore, we introduced TRPV1 knockout mice to further determine its function in epilepsy." (PMID 25713512, 2015). "Taken together, these results imply that hippocampal TRPV1 may play an important role in epilepsy." (PMID 25713512, 2015). "Previous studies have shown that TRPV channels, including TRPV1 and TRPV4, are involved in epileptogenic processes, demonstrating their roles in the pathological mechanisms of epilepsy." (PMID 40708193, 2025). "The mechanism of action of CBD in epilepsy involves its interaction with multiple molecular targets, including GPR55, TRPV1, and the adenosine system." (PMID 38891938, 2024). "Conversely, TRPV1 blockers such as CPZ demonstrated a protective role against neuronal apoptosis and epilepsy in the same rat model." (PMID 36902145, 2023). "Furthermore, the neuronal damage caused by complement 3 (C3) in astrocytic cultures treated with 4-AP was significantly reduced in the absence of the vanilloid receptor TRPV1, suggesting that TRPV1 in astrocytes participates in the neuronal loss elicited in epilepsy models." (PMID 34948035, 2021).